BEST1 (bestrophin 1)
Description:
Ligand-gated anion channel that allows the movement of anions across cell membranes when activated by calcium (Ca2+). Allows the movement of chloride and hydrogencarbonate. Found in a partially open conformation leading to significantly smaller chloride movement. Upon F2R/PAR-1 activation, the sequestered calcium is released into the cytosol of astrocytes, leading to the (Ca2+)-dependent release of L-glutamate into the synaptic cleft that targets the neuronal postsynaptic GRIN2A/NMDAR receptor resulting in the synaptic plasticity regulation (By similarity). Upon activation of the norepinephrine-alpha-1 adrenergic receptor signaling pathway, transports as well D-serine than L-glutamate in a (Ca2+)-dependent manner, leading to activation of adjacent NMDAR receptors and therefore regulates the heterosynaptic long-term depression and metaplasticity during initial memory acquisition (By similarity). Releases the 4-aminobutanoate neurotransmitter in a (Ca2+)-dependent manner, and participates in its tonic release from cerebellar glial cells (By similarity).
Synonyms: VMD2; BMD; BEST; RP50; ARB; Best1V1Delta2; TU15B
Tractability: Small molecule: a structure with a bound ligand is known. Antibody: UniProt places it where antibodies can reach, with high confidence; its Gene Ontology location is reachable by antibodies, with high confidence; UniProt predicts a signal peptide or a membrane-spanning region. PROTAC: ubiquitination databases record sites on it.
Gene: Protein-coding gene on chromosome 11 (61,950,063 to 61,965,515, forward strand). Ensembl gene ENSG00000167995.
Subcellular location: Cell membrane; Basolateral cell membrane
Pathways (Reactome):
Transport of small molecules: Stimuli-sensing channels
Gene Ontology:
Molecular function: bicarbonate channel activity; chloride channel activity; identical protein binding; intracellularly calcium-gated chloride channel activity; bicarbonate transmembrane transporter activity; ligand-gated channel activity; channel activity
Biological process: chloride transport; protein complex oligomerization; transepithelial chloride transport; chloride transmembrane transport; gamma-aminobutyric acid secretion, neurotransmission; glutamate secretion; monoatomic ion transmembrane transport; regulation of synaptic plasticity; visual perception; bicarbonate transport
Cellular component: basal plasma membrane; basolateral plasma membrane; chloride channel complex; plasma membrane; cytosol; membrane; membrane microdomain; presynapse
Genetic constraint (gnomAD): Loss-of-function variants: 54 observed, 52.92 expected, observed/expected ratio (o/e) 1.02, 90% interval 0.82 to 1.28. The upper end of that interval is the gene's LOEUF score, 1.28, which puts it in group 5 of 6, group 1 being the genes least tolerant of losing a copy. Missense variants: 557 observed, 617.7 expected, observed/expected ratio (o/e) 0.9, 90% interval 0.84 to 0.97. Synonymous variants: 229 observed, 240.14 expected, observed/expected ratio (o/e) 0.95, 90% interval 0.86 to 1.06.
Gene-disease validity (ClinGen):
ClinGen rates the evidence that BEST1 causes each of these diseases.
BEST1-related dominant retinopathy (autosomal dominant): Definitive. Any retinopathy caused by a heterozygous variant in the BEST1 gene.
Homologues: Orthologues: chimpanzee BEST1 (99% identical), macaque BEST1 (86% identical), dog BEST1 (79% identical), pig BEST1 (79% identical), rabbit BEST1 (74% identical), guinea pig BEST1 (68% identical), mouse Best1 (65% identical), rat Best1 (64% identical), tropical clawed frog best1 (54% identical), zebrafish best1 (53% identical), Drosophila melanogaster Best1 (38% identical), Drosophila melanogaster Best4 (31% identical), and 18 more. Paralogues in human: BEST3 (46% identical), BEST2 (44% identical), BEST4 (41% identical).
Diseases named in the same sentence as BEST1 in open-access papers:
BEST1 is named in the same sentence as 86 diseases in open-access papers, as found by Europe PMC text mining. Sharing a sentence is not in itself a finding about the gene and the disease. The quoted sentences say what the papers report.
autosomal recessive bestrophinopathy (71 papers, 2009 to 2026). Autosomal recessive bestrophinopathy (ARB) is a retinal dystrophy, characterized by central visual loss in the first 2 decades of life, associated with an absent electrooculogram (EOG) light rise and a reduced electroretinogram (ERG). "Pathogenic variants in BEST1 give rise to a spectrum of inherited retinal diseases, including Best vitelliform macular dystrophy, autosomal recessive bestrophinopathy, and adult-onset vitelliform dystrophy." (PMID 42222334, 2026). "It is the most frequent among the five distinct degenerative disorders linked to mutations in the BEST1 (VMD2) gene, collectively known as “bestrophinopathies” (Ref." (PMID 39860622, 2025). "Autosomal recessive bestrophinopathy (ARB) is a rare retinal dystrophy caused by homozygous or compound heterozygous null variants in the BEST1 gene." (PMID 40414863, 2025). "This work aims at documenting the founder effect of a novel variant in the BEST1 gene causing autosomal recessive bestrophinopathy and determining its variable clinical features." (PMID 40414863, 2025). "Autosomal recessive bestrophinopathy is a rare inherited retinal disease caused by pathogenic variants in the BEST1 gene." (PMID 40722697, 2025). "Bestrophinopathies are a group of inherited retinal disorders caused by mutations in the BEST1 gene, which encodes the bestrophin-1 protein." (PMID 40429522, 2025). "To date, over 447 variants in the BEST1 gene have been detected and 158 mutations have been correlated to bestrophinopathy cases." (PMID 40414863, 2025). "Variants in BEST1 cause a range clinically heterogeneous retinal dystrophies, including autosomal dominant macular dystrophy, autosomal recessive bestrophinopathy (ARB), and the overlapping phenotypes of autosomal dominant vitreoretinochoroidopathy and RP." (PMID 38219857, 2024). "Bestrophinopathy is the collective term of a phenotypically heterogeneous group of degenerative ocular diseases caused by mutations in the Bestrophin (BEST) genes, specifically the BEST1 gene." (PMID 38500685, 2024). "Bestrophinopathy represents a term to define a heterogenous group of IRDs characterized by mutations of the BEST1 gene encoding for bestrophin-1." (PMID 38610844, 2024). "Mutations in the BEST1 gene causes five clinically recognized retinal dystrophies, collectively referred to as bestrophinopathies, of which Best’s vitelliform dystrophy is the most common." (PMID 39011458, 2024). "Mutations in the BEST1 gene have been linked to bestrophinopathies, including Best disease, which exhibits symptoms overlapping with AMD, particularly in forms with late onset." (PMID 37761846, 2023). "Mutations in the BEST1 gene are associated with a group of untreatable inherited retinal dystrophies (IRDs) called bestrophinopathies, caused by protein instability and loss-of-function of the Best1 protein." (PMID 37110551, 2023). "Mutations in the BEST1 gene lead to a set of inherited retinal dystrophies (IRDs) called bestrophinopathies, caused by protein instability and loss of function of the Best1 protein." (PMID 37570721, 2023). "Mutations in the BEST1 gene are associated with a group of inherited retinal dystrophies (IRDs) called bestrophinopathies, caused by protein instability and loss-of-function of the Best1 protein." (PMID 37110551, 2023). "Bestrophinopathies are a group of retinal diseases whose common characteristic is the presence of a mutation in BEST1 gene in the affected patient." (PMID 35882966, 2022). "Bestrophinopathy is a spectrum of inherited macular degenerations caused by mutations in the BEST1 gene." (PMID 35885980, 2022). "A wide range of ocular phenotypes resulting from mutations in the BEST1 gene have been described and are collectively termed bestrophinopathies." (PMID 36527004, 2022). "Mutations in the BEST1 gene are associated with a wide range of ocular phenotypes, including autosomal recessive bestrophinopathy (ARB)." (PMID 35768830, 2022).
autosomal recessive bestrophinopathy (continued). "We recently identified several gain-of-function mutations, which enhance the channel activity when transiently expressed in HEK293 cells but still cause bestrophinopathy, suggesting the physiological importance of maintaining normal BEST1 functionality." (PMID 34061021, 2021). "The bestrophinopathies are a spectrum of inherited retinal dystrophies caused by pathogenic variation in the Bestrophin1 protein, encoded by the BEST1 gene." (PMID 33039401, 2021). "Autosomal recessive bestrophinopathy results from biallelic variants in BEST1 and is considered the null phenotype." (PMID 33039401, 2021). "Conventionally, BEST1 autosomal dominant mutations are identified when the mutation is present on just one of the two BEST1 alleles in a bestrophinopathy patient." (PMID 34061021, 2021). "Autosomal recessive bestrophinopathy conceivably should be amenable to a similar therapeutic approach, and a recent study using gene therapy to treat the canine model of BEST1-associated retinopathy confirmed this." (PMID 33039401, 2021). "A key question regarding the pathology of bestrophinopathies is how each BEST1 mutation specifically affects the channel activity, eventually resulting in retinal degeneration." (PMID 34061021, 2021). "Except for ARB, all other bestrophinopathies are the result of autosomal dominant mutations in BEST1, but available in vivo disease models have their limitations to characterize the dominant phenotype." (PMID 32967234, 2020). "Autosomal recessive bestrophinopathy (ARB) is caused by homozygous or compound heterozygous mutations in the BEST1 gene and always accompanied with refractory angle-closure glaucoma (ACG)." (PMID 32646389, 2020). "Mutations of the BEST1 gene can cause a series of retinal degenerative diseases which are named as the “bestrophinopathies”." (PMID 31969119, 2020). "Based on our results on the molecular mechanisms of pathologic BEST1 variants we classified the mutations causing the distinct bestrophinopathies into five different classes (I–V)." (PMID 32111077, 2020). "The present study provides a deeper insight into distinct molecular mechanisms of the three bestrophinopathies facilitating functional categorization of the more than 300 known BEST1 mutations that result into the distinct retinal phenotypes." (PMID 32111077, 2020). "Here, we investigated a large number of patient-derived hiPSC-RPEs harboring pathologic BEST1 mutations associated with three distinct phenotypes within the group of bestrophinopathies." (PMID 32111077, 2020). "Our exemplar protein, bestrophin 1, is a Cl− channel that is mutated in autosomal dominant and recessive bestrophinopathies." (PMID 32421148, 2020). "To date, more than 250 distinct mutations were identified in BEST1 in various forms of bestrophinopathies." (PMID 30781664, 2019). "Along with bestrophinopathies, mutated BEST1 was reported in patients with retinitis pigmentosa-50 (RP50; OMIM 613194)." (PMID 30781664, 2019). "Mutations in BEST1 have been associated with a range of clinically recognized ocular disorders in humans, collectively termed as bestrophinopathies." (PMID 30781664, 2019). "BEST1 is a Ca2+-activated Cl− channel predominantly expressed in retinal pigment epithelium (RPE), and over 250 genetic mutations in the BEST1 gene have been identified to cause retinal degenerative disorders generally known as bestrophinopathies." (PMID 31836750, 2019). "A large number of BEST1 mutations associated with bestrophinopathies have been reported in previous studies conducted on various populations from different ethnic groups, but none on near Eastern populations." (PMID 30781664, 2019). "Together, our findings underscore the great potential of gene augmentation therapy in treating bestrophinopathies, including those caused by BEST1 dominant mutations." (PMID 31836750, 2019). "Mutations in BEST1 cause a wide range of ocular phenotypes which are collectively termed Bestrophinopathy." (PMID 31766397, 2019).
autosomal recessive bestrophinopathy (continued). "In this study, we analyzed four Indian families with clinically diagnosed bestrophinopathy using whole exome sequencing and identified novel BEST1 mutations." (PMID 29976937, 2018). "The diseased cells showed slightly higher expression of BEST1, which is implicated in various bestrophinopathies." (PMID 30572641, 2018). "Mutations in the gene BEST1 usually cause bestrophinopathies, such as the rare progressive diseases Best vitelliform macular dystrophy (BVMD) and autosomal recessive bestrophinopathy (ARB)." (PMID 30498755, 2018). "It is reported that more than 300 distinct BEST1 mutations have been found in sporadic patients and families affected by various bestrophinopathies." (PMID 30498755, 2018). "A clinical feature of bestrophinopathies associated with BEST1 mutations is abnormal electrooculogram (EOG) light peak (LP), measured by the maximum transepithelial potential produced by RPE upon light exposure." (PMID 29063836, 2017). "Reduced LP is a pathognomonic phenotype associated with BEST1 mutations in bestrophinopathy patients." (PMID 29063836, 2017). "Autosomal recessive bestrophinopathy (ARB) is a retinopathy caused by mutations in the bestrophin-1 protein, which is thought to function as a Ca2+-gated Cl− channel in the basolateral surface of the retinal pigment epithelium (RPE)." (PMID 27519691, 2016). "Mutations in the BEST1 gene constitute an underlying cause of juvenile macular dystrophies, a group of retinal disorders commonly referred to as bestrophinopathies and usually diagnosed in early childhood or adolescence." (PMID 24143172, 2013). "Overlapping clinical presentation between BVMD and other bestrophinopathies, caused by well over 100 different mutations in BEST1, demonstrates the complexity of genotype–phenotype associations." (PMID 21197113, 2010). "Mutations in the BEST1 (also known as VMD2) gene cause several human retinal disorders grouped as bestrophinopathies." (PMID 21197113, 2010). "Two mutations in canine BEST1 (cBEST1) have previously been described in different dog breeds and established the canine bestrophinopathy models." (PMID 21197113, 2010). "Mutations in bestrophin 1 (BEST1) are associated with a group of retinal disorders known as bestrophinopathies in man and canine multifocal retinopathies (cmr) in the dog." (PMID 21197113, 2010). "Bestrophinopathies are a group of inherited retinal diseases caused by mutations in the BEST1 gene." (PMID 40733213, 2025). "Mutations in BEST1 have also been associated with other clinically distinct retinal degenerative diseases including Autosomal Recessive Bestrophinopathy (ARB), Autosomal Dominant Vitreoretinochoroidopathy (ADVIRC), Adult Vitelliform Macular Degeneration (AVMD), and Retinitis Pigmentosa 50 (RP50)." (PMID 35806438, 2022). "Our results suggest that bestrophinopathies caused by autosomal dominant mutations of BEST1 may serve as a paradigm to address the influence of AEI in Mendelian disorders." (PMID 34061021, 2021). "To date, over 250 distinct BEST1 mutations have been identified from bestrophinopathy patients, but their pathological mechanisms remain unclear." (PMID 34061021, 2021). "In this study, we first demonstrated that 4PBA, a well-established chemical chaperone, could restore the function in the same way to mutant bestrophin 1 causing an autosomal dominant bestrophinopathy as it can to a recessive one." (PMID 32421148, 2020). "Therefore, understanding the mechanisms of BEST1 disease-causing mutations and designing strategies to restore the damaged cellular function are critical for developing treatments for bestrophinopathies." (PMID 31836750, 2019). "Interestingly, the ARB families A and B carry homozygous mutations while family C was a compound heterozygote with a mutation in an alternate BEST1 transcript isoform, highlighting a role for alternate BEST1 transcripts in bestrophinopathy." (PMID 29976937, 2018).
autosomal recessive bestrophinopathy (continued). "All mutants mentioned in that study showed a significant reduction in anion conductance, indicating that disease-associated missense mutations in bestrophin-1 affect cellular trafficking and anion conductance and thus may be a common cause of bestrophinopathy." (PMID 30498755, 2018). "Finally, mutations in BEST1 give rise to autosomal recessive and dominant bestrophinopathies, including best disease, autosomal dominant adult-onset vitelliform macular dystrophy, and autosomal dominant vitreoretinochoroidopathy." (PMID 29053642, 2017). "Therefore, understanding how disease-causing mutations affect the biological function of BEST1 in the retina is critical for elucidating the pathology of bestrophinopathies and developing rational therapeutic interventions." (PMID 29063836, 2017). "Autosomal recessive bestrophinopathy (ARB) is caused by biallelic mutations in BEST1." (PMID 21203346, 2010). "Autosomal recessive bestrophinopathy (ARB) is a subtype of bestrophinopathy caused by biallelic mutations of the BEST1 gene, which affect the retinal pigment epithelium (RPE)." (PMID 39029076, 2024). "Autosomal recessive bestrophinopathy (ARB) is a rare retinal dystrophy caused by autosomal recessively mutations in bestrophin 1 (BEST1) gene." (PMID 37041514, 2023). "Bestrophinopathies are one of the most common macular dystrophies in the world, with an estimated prevalence ranging from 1.5 to 20 people out of 100,000 in various studies, and are associated with mutations in the BEST1 gene, which has a wide spectrum of phenotypic variations." (PMID 36835965, 2023). "Best vitelliform macular dystrophy (BVMD) and autosomal recessive bestrophinopathy (ARB) are two of the clinically distinct diseases associated with mutations in BEST1." (PMID 37570721, 2023). "Autosomal recessive bestrophinopathy (ARB) is a rare subtype of bestrophinopathy caused by biallelic mutations of the BEST1 gene." (PMID 35885980, 2022). "As the majority of the over 250 documented BEST1 disease-causing mutations are autosomal dominant and display loss-of-function when tested in vitro, our results indicate an important role of allele-specific epigenetic control in the development of bestrophinopathies." (PMID 34061021, 2021). "Two years later, Burgess et al9 concluded that this condition was a fourth BEST1-associated phenotype and coined the term autosomal recessive bestrophinopathy (ARB)." (PMID 33039401, 2021). "Autosomal recessive bestrophinopathy (ARB) is a retinal degenerative disorder caused by BEST1 mutations with autosomal recessive inheritance." (PMID 31969119, 2020). "Autosomal recessive bestrophinopathy (ARB) is caused by homozygous or compound heterozygous mutations in the BEST1 gene." (PMID 32646389, 2020). "Bestinopathies are a spectrum of retinal disorders associated with mutations in BEST1 including autosomal recessive bestrophinopathy (ARB) and autosomal dominant Best vitelliform macular dystrophy (BVMD)." (PMID 29976937, 2018). "Autosomal recessive bestrophinopathy (ARB) is caused by mutations in the gene BEST1 which encodes bestrophin 1 (Best1), an anion channel expressed in retinal pigment epithelial (RPE) cells." (PMID 29540715, 2018). "The functional rescue achieved with 4PBA is significant because it suggests that this drug, which is already approved for long-term use in infants and adults, might represent a promising therapy for the treatment of ARB and other bestrophinopathies resulting from missense mutations in BEST1." (PMID 27519691, 2016). "Identification of additional families with recessive bestrophinopathy and detailed characterization of the clinical phenotypes of homozygous and heterozygous individuals will assist in establishing the phenotype–genotype correlations in patients with BEST1-associated diseases." (PMID 27071392, 2016). "Abnormalities in the BEST1 gene have recently been recognised as causing autosomal recessive bestrophinopathy (ARB)." (PMID 24859690, 2014).